GAREM2 (GRB2 associated regulator of MAPK1 subtype 2)
Description:
Probable adapter protein that may provide a link between cell surface epidermal growth factor receptor and the MAPK/ERK signaling pathway.
Synonyms: FAM59B; GAREML; KIAA2038; FLJ00375
Tractability: No criterion of Open Targets' tractability assessment is met for any kind of drug.
Gene: Protein-coding gene on chromosome 2 (26,173,088 to 26,189,663, forward strand). Ensembl gene ENSG00000157833.
Subcellular location (Human Protein Atlas): Cytosol
Genetic constraint (gnomAD): Loss-of-function variants: 26 observed, 42.81 expected, observed/expected ratio (o/e) 0.61, 90% interval 0.44 to 0.84. The upper end of that interval is the gene's LOEUF score, 0.84, which puts it in group 3 of 6, group 1 being the genes least tolerant of losing a copy. Missense variants: 958 observed, 980.62 expected, observed/expected ratio (o/e) 0.98, 90% interval 0.93 to 1.03. Synonymous variants: 487 observed, 427.11 expected, observed/expected ratio (o/e) 1.14, 90% interval 1.06 to 1.23.
Homologues: Orthologues: chimpanzee GAREM2 (99% identical), macaque GAREM2 (98% identical), dog GAREM2 (91% identical), rat Garem2 (89% identical), mouse Garem2 (88% identical), guinea pig GAREM2 (76% identical), pig GAREM2 (70% identical), rabbit GAREM2 (66% identical), tropical clawed frog garem2 (59% identical), zebrafish gareml (51% identical). Paralogues in human: GAREM1 (44% identical).
Diseases named in the same sentence as GAREM2 in open-access papers:
GAREM2 is named in the same sentence as 5 diseases in open-access papers, as found by Europe PMC text mining. Sharing a sentence is not in itself a finding about the gene and the disease. The quoted sentences say what the papers report.
Anxiety (2 papers, 2019 to 2025). Intense feelings of nervousness, tension, or panic often arise in response to interpersonal stresses. "For rs1025542, located close to the GAREM2 gene, the G allele has been linked to increased risks of anxiety and depression." (PMID 40002435, 2025). "Our results of the EPM test suggested that, GAREM2 KO mice demonstrated lower anxiety compared with WT mice." (PMID 31718706, 2019). "Although we could not detect the statistical difference for multiple hypothesis testing in most of these behavioral results, except for anxiety index in the open field test, GAREM2 KO mice consistently tended to be less anxiety in different tests." (PMID 31718706, 2019). "GAREM2 KO mice presented a higher anxiety index compared to the WT mice." (PMID 31718706, 2019). "Consequently, GAREM2 KO mice were more active and exhibited lower anxiety than the WT mice." (PMID 31718706, 2019). "However, comprehensive behavioral battery analysis indicated GAREM2 KO mice exhibited low anxiety-like behavior in the EPM test, tended to higher social approaching behavior, and increased exploratory activity / reduced novelty-induced anxiety in the open field test." (PMID 31718706, 2019).
neuroblastoma (1 paper, 2019). Neuroblastoma (NB) is the most common solid, extracranial childhood tumor. "In the previous study, the result of knockdown experiments using small interfering RNA (siRNA) in a neuroblastoma cell line (SH-SY5Y) suggested that GAREM2 is a regulator of IGF-1-induced neurite outgrowth." (PMID 31718706, 2019).
neurodegenerative disease (2 papers, 2019 to 2021). A disorder of the central nervous system characterized by gradual and progressive loss of neural tissue and neurologic function. "On the meanwhile, GAREM2 has been identified as a new positive effecter related for two neurodegenerative diseases–Alzheimer’s and Huntington’s disease." (PMID 31718706, 2019). "Recent report described that GAREM2 has been identified as a candidate molecule of neurodegenerative diseases." (PMID 31718706, 2019). "Recent genome-wide research identified GAREM2 as a candidate of neurodegenerative diseases." (PMID 31718706, 2019).
GAREM2 also shares sentences with these, for which no sentence is quoted: dementia (1 paper); depression (1).